MERTK (MER proto-oncogene, tyrosine kinase)
Diseases named in the same sentence as MERTK in open-access papers (continued):
Sharing a sentence is not in itself a finding about the gene and the disease.
liver fibrosis (continued). "In this line, targeting Axl reduced or even prevented hepatic fibrosis in mice with high-fat diets, while MerTK protected primary murine hepatocytes against lipid-induced toxicity via activation of Akt." (PMID 34771611, 2021). "Another study supported these findings by showing that hepatic fibrosis is only attenuated in Axl-/- mice compared to Axl-/-/MerTK-/- mice." (PMID 34771611, 2021). "Conversely, a recent study showed that macrophage-specific MerTK expression promotes liver fibrosis by upregulation of Erk-TGF-β signaling in liver macrophages, which induces activation of HSCs." (PMID 34771611, 2021). "Together, these findings identify Axl as a driver of liver fibrosis by activating HSCs, whereas MerTK on macrophages acts as a pro-fibrotic in NASH-driven fibrosis and possesses an anti-fibrotic role in CCl4-driven fibrosis through apoptotic cell clearance." (PMID 34771611, 2021). "The preferential binding of IRF1 to the A allele compared to the C allele would downregulate MERTK in patients carrying the A allele, protecting against CHC liver fibrosis and HCC." (PMID 31583026, 2019). "Gas6/TAM system (mainly, Axl and MERTK) has in fact recently emerged as an important player in the progression of liver fibrosis." (PMID 31583026, 2019). "One study in 2342 chronic hepatitis C patients found that SNPs in two functionally related gene, MERTK and TULP1(tub like protein 1), encoding factors involved in the macrophage mediated phagocytosis of apoptotic cells were associated with liver fibrosis progression." (PMID 39201329, 2024). "Of note, in a genome-wide association study and several independent replication cohorts of patients with NASH or hepatitis C virus-related chronic hepatitis, naturally occurring variations in MERTK contributed to the development and progression of liver fibrosis." (PMID 36572816, 2023). "Interestingly, chronic HIV infection under long-term cART in hu-mice led to liver fibrosis with induction of liver hepatitis and accumulation of MerTK+/M2-like macrophages." (PMID 35639478, 2022). "Therefore, Axl-/- but not Axl-/-/MerTK-/- mice display less fibrotic livers and highlight the importance of MerTK proficient macrophages in resolving liver fibrosis." (PMID 34771611, 2021). "However, clinical studies in NAFLD- and HCV-induced liver fibrosis presented ambiguous functions of MerTK." (PMID 34771611, 2021). "However, this approach must consider the possible adverse effects of heightened MerTK function on cancer and possibly pathologic liver fibrosis." (PMID 30980657, 2019). "Indeed, in genome-wide association studies, it has been reported that the MERTK locus rs4374383 G > A correlates with decreased hepatic MerTK expression, thus protecting against liver fibrosis in chronic hepatitis C and NAFLD." (PMID 31191323, 2019). "Regarding non-alcoholic fatty liver disease (NAFLD) among patients not infected by HCV, the MERTK rs4374383 A allele has also been associated with lower risk of liver fibrosis." (PMID 30477195, 2018). "Thus, it indicates the possible role of MerTK in liver fibrosis." (PMID 39201329, 2024). "Moreover, further studies should be conducted to evaluate the impact of the MERTK rs4374383 SNP on liver fibrosis and the development of hepatocellular carcinoma after HCV elimination since patients with advanced fibrosis or cirrhosis are still at risk of disease progression." (PMID 30477195, 2018). "In nonalcoholic steatohepatitis, limiting ADAM17 activity increases MerTK expression in macrophages, which further induces TGF-β1 production, leading to the activation of hepatic stellate cells by TGF-β1 to encourage liver fibrosis." (PMID 40224489, 2025). "European GWAS have identified SNPs in MERTK, GLT8D2, TULP1, and RNF7 as the genetic factors responsible for liver fibrosis progression in chronic hepatitis C during the natural course." (PMID 26352693, 2015).
liver fibrosis (continued). "Similarly, it has been reported that MerTK signaling resulted in the activation of ERK-TGFβ1 pathway that stimulates HSCs and promotes liver fibrosis in MASH." (PMID 38298195, 2024). "Macrophage MerTK activation is enhanced in nonalcoholic steatohepatitis (NASH) due to suppression of its cleavage by ADAM17, which activates hepatic stellate cells (HSC) via the ERK-TGFβ1 pathway to promote liver fibrosis." (PMID 37422464, 2023). "Specifically, MerTK signaling in macrophages activates the ERK1/2 pathway leading to increased TGFβ expression, and myeloid cell-specific targeting of MerTK in mice fed a NASH-inducing diet partially protects from liver fibrosis development." (PMID 35805998, 2022). "MERTK role has been explored in a preclinical model, concluding that macrophages enriched in MERTK activate hepatic stellate cells in NASH by inducing TGF-β1 pathway therefore inducing liver fibrosis." (PMID 34899679, 2021).
lung cancer (17 papers, 2015 to 2026). A malignant neoplasm involving the lung. "Axl and MERTK are overexpressed in lung cancer, and MERTK inhibitors reduce distant metastases in NSCLC models." (PMID 40079009, 2025). "MerTK is overexpressed or ectopically expressed in a wide variety of cancers, including leukemia, non–small cell lung cancer, and glioblastoma, and can potentially activate several canonical oncogenic signaling pathways." (PMID 38443968, 2024). "The inhibition of MerTK by AZD7762 was validated using an in vitro homogeneous time-resolved fluorescence (HTRF) assay and through monitoring the decrease in phosphorylated MerTK in two lung cancer cell lines." (PMID 33114206, 2020). "Analysis of mouse lung tumors revealed MerTK staining on tumor cells and in vitro studies showed that Gas6 increased proliferation of human lung cancer cell lines." (PMID 31903163, 2019). "Active MerTK was found in human lung cancer cell lines in culture and addition of Gas6 induced proliferation of these cells." (PMID 31903163, 2019). "Mer590, a monoclonal antibody against MerTK, decreased MerTK expression in several lung cancer cell lines as well as increased apoptosis, sensitivity to carboplatin and decreased colony formation." (PMID 31088471, 2019). "Notably, some of the nine differential proteins (3HAO, ASAH1, CHMP5, FPRP, IBP3, MERTK, MUC18, NRP1, and PRIO) in tumor-forming rats have already been reported to be associated with lung cancer biomarkers/pathology/mechanisms or ovarian cancer metastasis." (PMID 32678190, 2020). "MERTK and AXL mediate multiple oncogenic phenotypes in lung cancer, including tumor cell growth, survival, metastasis, invasion, and drug resistance, and are potential targets for lung cancer treatment." (PMID 34830794, 2021). "We found that the combination of MerTK ASO with radiotherapy and anti-PD1 or anti-CTLA4 significantly enhances the anti-tumor immune response and improves treatment efficacy in both the primay, irradiated tumors and secondary, unirradiated tumors in an anti-PD1-resistant lung cancer model." (PMID 38443968, 2024). "This is especially important given the known resistance to immune checkpoint blockade in EGFRMT lung cancers relative to that in NSCLC patients without EGFR mutations and the possibility that targeting MERTK could overcome this immune resistance." (PMID 35708914, 2022). "Moreover, AXL and the other TAM receptors (TYRO3 and MERTK) have been reported as key mediator of chemoresistance in neuroblastoma through induction of EMT and in lung cancer through the regulation of mitogen-activated protein kinase (MAPK) and FAS signaling pathways." (PMID 34745951, 2021).
retinal dystrophies (16 papers, 2010 to 2025). "In patients with NPDR compared to those with DM alone, MerTK—a gene implicated in inherited retinal dystrophies due to its mutations—was notably downregulated in PBMCs." (PMID 39845889, 2024). "MERTK mutations account for approximately 1% of all RP cases and have been reported in several families with retinal dystrophy." (PMID 33672445, 2021). "Two large-scale molecular surveys of retinal dystrophies revealed ~3% of RP cases are attributable to MERTK mutations." (PMID 34970569, 2021). "Screening of DNA samples from individuals with autosomal-recessive RP (ARRP) showed that MERTK mutations are a rare cause of retinal dystrophy in humans, affecting less than 1% of the probands." (PMID 21677792, 2011). "Screening of patients with LCA and childhood onset retinal dystrophies using the Asper Ophthalmics LCA chip allowed us to identify a further patient with a previously reported MERTK mutation." (PMID 20300561, 2010). "Two hundred and ninety-two probands with autosomal recessive, childhood onset, retinal dystrophies were analyzed using the Asper Ophthalmics Leber congenital amaurosis chip to screen for known MERTK mutations." (PMID 20300561, 2010). "In conclusion, this study adds to the understanding of the genetic and clinical characteristics of individuals with MERTK-related retinal dystrophies and underlines that CNV analysis should be added to the genetic evaluation of individuals suspected of having retinal dystrophy." (PMID 33353011, 2020). "Mutations in the MERTK gene cause retinal dystrophies in humans and in animal models." (PMID 26458944, 2015). "MERTK-related retinal dystrophies share many features with those due to RPE65 mutations and could therefore be a good target for future viral-mediated gene therapy in humans." (PMID 21677792, 2011). "Mutations in MERTK are a rare cause of retinal dystrophy in humans." (PMID 20300561, 2010). "Analysis of the MERTK locus identified a total of ten Alu Y repeats; nonhomologous recombination involving other Alu Y repeats could therefore be involved in other MERTK-associated retinal dystrophies." (PMID 20300561, 2010). "However, in comparison to other genes involved in retinal dystrophies, the reporting of new mutations in MERTK has been slow, with only a further five mutations having been described since the initial study." (PMID 20300561, 2010). "The MERTK truncating variant p.Arg732Ter detected in current study is a loss of function variant due to the degradation of expressed aberrant transcript by NMD that may lead to retinal dystrophies." (PMID 37165311, 2023). "Additionally, we assessed whether Gas6 NPs enhanced the therapeutic effects of gene therapy in RCS rat model of MERTK-associated retinal dystrophy." (PMID 34970569, 2021). "In addition to symptoms seen in other generalized retinal dystrophies, the fundi of patients with MERTK mutations develop an early bull’s eye central atrophy, which may guide the mutation analysis." (PMID 21677792, 2011). "Within the spectrum of RP-related retinal dystrophy, several gene therapy studies have been published for the replacement of specific mutated genes, such as RPGR MERTK, RLBP1 and PDE6B." (PMID 37762059, 2023). "The herein presented case is one of very few examples for this mechanism observed and described in inherited retinal dystrophy, including UPD of chromosome 2 in a patient with a homozygous mutation in MERTK, and the first for ACHM." (PMID 34360608, 2021). "Shortly after the identification of a Mertk mutation in a rat—an extensively studied model of retinal dystrophy —at the Royal College of Surgeons (RCS), Gal and coworkers reported the first three mutations in the human ortholog MERTK." (PMID 21677792, 2011). "Indeed, 14 genes that are differentially bound by PRPF8Y2334N in RPE cells have been associated with various retinal dystrophies and four genes (MVK, PDSS1, MERTK and SEMA4A) are involved in RP." (PMID 40045025, 2025).
retinal dystrophies (continued). "Furthermore, 24 families had VUS, two families with variants in genes related to non-syndromic EoHM (SCO2 and ZNF644) and seven families with variants in genes associated with other retinal dystrophies (TRPM1, CACNA1F, KCNV2, RDH5 and MERTK)." (PMID 35457050, 2022). "The 91-kb deletion encompassing exons 1–7 of MERTK is a common founder mutation in the Faroe Islands, responsible for around 30% of RP, and together with mutations in protocadherin 21 (PCDH21) accounts for more than half of the retinal dystrophy cases." (PMID 21677792, 2011). "In addition, the reported variants were of clinical significance as the PDE6C variant was detected novel, whereas TULP1, MERTK, and MYO7A variants were detected rare and first time found segregating with retinal dystrophies in Pakistani consanguineous families." (PMID 37165311, 2023). "In the case of MERTK and ARL6 where EoHM was not reported, however, this manifestation might be a second consequence of the genetically determined retinal dystrophy." (PMID 35457050, 2022).
acute myeloid leukemia (13 papers, 2018 to 2026). Acute myeloid leukemia (AML) is a group of neoplasms arising from precursor cells committed to the myeloid cell-line differentiation. "Apart from this, MERTK is found to be overexpressed in heterogeneous forms of cancer that include lung cancer, breast cancer, acute myeloid leukemia, and melanoma, among others." (PMID 39635932, 2024). "The molecule is under trial for treating relapsed or refractory acute myeloid leukemia via inhibition of MERTK." (PMID 39635932, 2024). "For instance, approximately 80–90% of patients diagnosed with acute myeloid leukemia (AML) show elevated levels of MERTK." (PMID 39062902, 2024). "Similarly, MRX-2843, a dual MerTK/Axl inhibitor, has shown immune-modulatory activity in acute myeloid leukemia (AML), lung adenocarcinoma, ovarian cancer, and pediatric gliomas, where it reprogrammed tumor-associated macrophages and improved T cell function." (PMID 40821795, 2025).
glioma (13 papers, 2014 to 2025). A benign or malignant brain and spinal cord tumor that arises from glial cells (astrocytes, oligodendrocytes, ependymal cells). "The agent is also being explored in early-phase trials for pediatric gliomas, where MerTK is implicated in immune evasion and tumor proliferation." (PMID 40821795, 2025). "MERTK inhibitors have been confirmed to be used in combination with radiotherapy or chemotherapy in glioma, NSCLC, head and neck squamous cell carcinoma, and other tumors to achieve better efficacy." (PMID 37101691, 2023). "Myosin light chain 2 expression and phosphorylation are closely connected to MerTK activity, suggesting that the role of MerTK in glioma cell invasion is mediated through the contractility of actin." (PMID 37786890, 2022). "Noteworthy, when we compared the tyrosine kinase receptors AXL and MERTK in U87MG cells vs. MDM, AXL was highly expressed only in glioma cells, whilst MERTK was expressed in MDM which denote the difference in the cell type source during heterotypic co-culture." (PMID 34065977, 2021). "We confirmed the essential role of MerTK with subcutaneous and intracranial models of glioma utilizing lines that had genetic inhibition of MerTK, this allows for both exclusive targeting as well as more thorough inhibition of signaling." (PMID 24658326, 2014). "Furthermore, depletion of MerTK disrupts the round morphology of glioma cells and decreases their invasiveness." (PMID 31467533, 2019). "Additionally, the expression and phosphorylation of myosin light chain strongly correlated with activation of MerTK, suggesting that the effect of MerTK on glioma cell invasion is mediated by the ability of acto-myosin to contract." (PMID 31467533, 2019). "Additionally, glioma cells with elevated MerTK activation showed greater resistance to pro-apoptotic stimuli as well as increased invasive potential compared to cells with MerTK expression silenced." (PMID 25980499, 2015). "Similarly, MRX-2843, a dual MerTK/Axl inhibitor, has shown preclinical synergy with checkpoint inhibitors in AML, gliomas, and ovarian cancer by blocking myeloid-driven immune suppression." (PMID 40821795, 2025). "Recent studies have demonstrated overexpression of MerTK or Axl in astrocytic tumours of all grades, and co-expression of MerTK and Axl in all high grade glioma tissue samples, relative to little or no expression in normal CNS." (PMID 25980499, 2015). "Previous reports have established the importance of Axl in human and xenograft glioma tumor growth, although those reports did not explore the presence or relative inhibition of MerTK." (PMID 24658326, 2014).
non-small cell lung carcinoma (12 papers, 2015 to 2025). A group of at least three distinct histological types of lung cancer, including non-small cell squamous cell carcinoma, adenocarcinoma, and large cell carcinoma. "Dual inhibition strategies have also emerged, including UNC9435, the first TYRO3/MERTK dual inhibitor and macrocyclic MERTK/AXL inhibitors with promising activity in non-small cell lung cancer." (PMID 41166341, 2025). "MERTK monoclonal antibodies promoted the apoptosis of triple-negative breast cancer and non-small cell lung cancer." (PMID 37475048, 2023). "Nuclear PD-L1, coupled with transcription factor Sp1, activates the MERTK signaling pathway by regulating Gas6 mRNA synthesis and promoting Gas6 secretion, which promotes cell proliferation in non-small-cell lung cancer (NSCLC)." (PMID 35907881, 2022). "Of the TAMRs, MerTK has been shown to be expressed by a variety of tumor types, including non-small cell lung cancer (NSCLC)." (PMID 31903163, 2019). "MERTK is also expressed in other malignancies, including leukemia, melanoma, and non-small cell lung cancer, and mediates activation of proliferative and survival pathways in malignant cells." (PMID 27783662, 2016). "Moreover, its up-regulation has been shown in different cancer entities: 69 % of non-small cell lung cancers overexpress MERTK where it is involved in tumor growth and chemosensitivity." (PMID 27081701, 2016). "Previous work from our lab and work shown here demonstrated regulation of survivin protein levels downstream of MERTK in non-small cell lung cancer cells and a reduction in survivin protein in tumor cells treated with UNC2025, including the GBM cell lines U251 and A172." (PMID 27783662, 2016). "MERTK and AXL are members of the TAM family of receptor tyrosine kinases and are abnormally expressed in 69% and 93% of non-small cell lung cancers (NSCLCs), respectively." (PMID 34830794, 2021). "Expression of MERTK and/or AXL (members of the TAM family of receptor tyrosine kinases) provides a survival advantage for non-small cell lung cancer (NSCLC) cells and correlates with lymph node metastasis, drug resistance, and disease progression." (PMID 34830794, 2021).